IL13 (interleukin 13)
Diseases named in the same sentence as IL13 in open-access papers (continued):
Sharing a sentence is not in itself a finding about the gene and the disease.
allergic asthma (continued). "Pro-inflammatory factors such as IL-5, IL-13, TNF-α, and IL-6 play a leading role in the pathogenesis of allergic asthma, including the growth of eosinophils, the isotypic transition of B cells to IgE production, chemotaxis of neutrophils, and bronchial contraction." (PMID 39408735, 2024). "In the context of IL-13, the results of the VCN-treated animals were supported by a previously published work investigating the anti-inflammatory effect of 10mg/kg of vinpocetine in a model of allergic asthma in mice." (PMID 38750140, 2024). "Thus, we treated BMDMs with various allergic asthma-related cytokines, including TSLP, IL-33, IL-13, and IL-4." (PMID 38177117, 2024). "Serum was more effective than BALF in preconditioning BM-MSCs and led to a significant reduction in lung inflammatory cell counts and levels of TH2 cytokines (IL-4 and IL-13) and eotaxin, and lung function improved in a murine model of HDM-induced allergic asthma." (PMID 37007034, 2023). "Paeoniflorin can reduce the expression levels of IL-5, IL-13, IL-17, and eotaxin in the OVA-induced allergic asthma mice model, which may be concerned with the blocking of the MAPK pathway activation." (PMID 35431951, 2022). "At present, there is consensus that M2a cell is elicited by IL-4- and IL-13 and secret high levels of IL-13 and chemokines, including TARC and CCL24, that activate Th2 immunity and promotes eosinophil trafficking, which induces allergic asthma." (PMID 36175886, 2022). "In conclusion, our results suggests that estrogen can play a protective role in allergic asthma by negatively regulating IL-33 induced ILC2 and IL-5/IL-13 cytokine production, furthermore we demonstrated that this effect is regulated by NF-κB signaling pathway." (PMID 36506643, 2022). "Although they are few in number in circulating blood and lungs of healthy individuals, eosinophils are more frequent in allergic asthma and allergic bronchopulmonary aspergillosis (ABPA), as well as the Th2 cytokine repertory, comprised principally by IL-5 and IL-13." (PMID 36145419, 2022). "Furthermore, MX1, RSAD2, IFIT1, IFI27, OAS3, and SAMD9L levels correlated positively with IL-5, IL-13, and MUC5AC levels, which are the key mediators of allergic asthma." (PMID 36211429, 2022). "We confirmed that the OVA-induced allergic asthma is mainly driven by the Th2 response, following the production of IL-5 and IL-13, but not IL-4, and that PGT treatment greatly reduced such induction." (PMID 33374657, 2020). "IL-13 is thought to be the type 2 cytokine and key mediator of allergic asthma, yet it is considered to act via the pathway independent of immunoglobulin E and eosinophils." (PMID 31779093, 2019). "IL-4 or IL-13 production from iNKT cells is required for the development of allergic asthma in mouse models, while iNKT cells can produce IFN-γ, which can suppress the Th2 response and thereby prevent allergic asthma." (PMID 30210497, 2018). "IL13 is an immunoregulatory cytokine produced by TH2 cells that is critical to the pathogenesis of allergic asthma, operating through mechanisms independent of IgE and eosinophils." (PMID 30373671, 2018). "IgE production in allergic asthma patients is more dependent on IL-13 than in non-atopics, due to enhanced IL-13 production and to enhance IgE production in response to IL-13." (PMID 28057889, 2017). "We hypothesized that airway allergen challenge would induce an elevated expression profile of two critical Th2 cytokines, IL-4 and IL-13, in the HDM sheep model of allergic asthma." (PMID 26362930, 2015). "For instance, expression of the IL-4 receptor alpha, which is required for both IL-4 and IL-13 signalling is not required on smooth muscle cells for the development of experimental allergic asthma." (PMID 21677778, 2011).
allergic asthma (continued). "Earlier we identified the upregulation of factor XIII in allergic asthma and demonstrated that its abundance correlates with measures of pulmonary function (FEV1/FVC and reversibility of obstruction) and with markers of Th2 activity (IL13 and eosinophil influx)." (PMID 35590254, 2022). "Especially, it has been reported that miR-146a-5p could inhibit the proliferation and function (IL-13 secretion) of type II innate lymphoid cells (ILC2), efficiently protect mice against OVA-induced allergic asthma, and also modulate anti-fibrosis responses induced by TGF-β1-Smad signaling." (PMID 33407872, 2021). "ILC2 mainly produced IL-5 and IL-13, but not IL-4, in an allergic asthma model." (PMID 32915886, 2020). "Our data showed the Lineage-cells from both mugwort-allergic asthma group and HDM-allergic asthma group could produce significant amounts of IL-5 and IL-13 after the stimulation with IL-33 when compared to IL-2 alone (all P < 0.05, respectively), or medium alone (all P < 0.05, respectively)." (PMID 29449864, 2018). "A similar reduction in BAL inflammatory cells as well as reductions in BAL eotaxin and IL-13 with adiponectin overexpression was observed when we used a chronic OVA challenge protocol in which inflammation is dependent on mast cells, a feature relevant to human allergic asthma." (PMID 23861690, 2013). "Our group previously reported that IL-13 treatment of bronchial epithelial cells reduced SARS-CoV2 replication in donors with allergic asthma and not healthy children, suggesting there may be differential responses to IL-13 in rhinovirus between healthy and asthmatic epithelium." (PMID 41427379, 2025). "Patients with allergic asthma do not suffer increased morbidity from SARS-CoV-2 infections, possibly due to the protective effects of IL-13 and other type 2 cytokines." (PMID 36366439, 2022). "IL-13 itself was not differentially expressed in HDMS wheezers versus nonwheezers, however network analysis demonstrated that in wheezers it was connected to an extensive set of genes that have established roles in mouse models of allergic asthma." (PMID 29367592, 2018). "Thus, therapies targeting Type 2 signaling, such as monoclonal antibodies directed against IL-13, IL-5, IL-33, TSLP (thymic stromal lymphopoietin) or their receptors, or against IgE, have been effective in treating allergic asthma without inducing a substantial cost in parasite clearance." (PMID 34899381, 2021). "We further identified that the sorted ILC2s produced IL-5 and IL-13, and demonstrating there was a positive correlation between IL-13+ILC2s numbers and FeNO levels in pollen-allergic asthmatics, however, no similar results were found in HDM-allergic asthma patients." (PMID 29449864, 2018).
atopic dermatitis (291 papers, 2006 to 2026). "This skin disease is associated with atopic dermatitis and has been shown to improve with the treatment of dupilumab, an inhibitor of the IL-4 and IL-13 immune pathway." (PMID 40861695, 2025). "Psoriasis is a disease primarily driven by Th17 T-cells and associated IL-17 activation, whereas atopic dermatitis (AD) is characterized by a strong Th2 response with overproduction of IL-4 and IL-13." (PMID 41517378, 2025). "Various polymorphisms in the genes encoding IL-4, IL-13, and their receptors have been associated with a genetic predisposition to atopic dermatitis in both children and adults." (PMID 41002407, 2025). "The present finding was also in agreement with Chan (2018) that the specific diagnostic cytokines of atopic dermatitis are IL‐4 and IL‐13." (PMID 38648253, 2024). "IL-4 and IL-13 stimulate B cells to produce IgE and also promote the eosinophilic reaction, which is associated with atopic dermatitis and other accompanied atopic diseases." (PMID 39457662, 2024). "Th2 polarization facilitates S. aureus binding and colonization, and IL-4 and IL-13 inhibit skin production of AMPs, predisposing atopic dermatitis skin to S. aureus infections, which, in turn, further exacerbates skin inflammation and barrier defects." (PMID 39202657, 2024). "It has been reported that the specific diagnostic cytokines of atopic dermatitis are IL‐4 and IL‐13." (PMID 38648253, 2024). "The significant positive correlations between IgE and IL‐4 and IL‐13 indicate that the immunologic response to type I hypersensitivity reaction in atopic dermatitis is caused by environmental allergens in dogs by increasing IgE, IL‐4 and IL‐13 production." (PMID 38648253, 2024). "To mimic skin barrier dysfunction, we treated keratinocytes and full-thickness skin equivalents with IL-4 and IL-13, cytokines that are implicated in atopic dermatitis, and confirmed the downregulation of tight junction and differentiation markers." (PMID 39329899, 2024). "The presence of IL-4 and IL-13 in skin lesions of atopic dermatitis is associated with the stimulation of thymic stromal lymphopoietin (TSLP) production in keratinocytes upon exposure to external substances." (PMID 37630370, 2023). "Atopic dermatitis, in contrast, is believed to be mediated by Th2 and Th22, and the associated secretion of IL-4/IL-13 and IL-22, respectively." (PMID 37138890, 2023). "For instance, IL-4 and IL-13, pathogenic for atopic dermatitis, and IL-17A, pathogenic for psoriasis, lead to a downregulation of filaggrin." (PMID 38132754, 2023). "The type 2 cytokines interleukins (IL)-4, IL-13, and IL-33 are central in the inflammatory pathogenesis of atopic dermatitis and implicated to play an additional role in itch sensation in murine models." (PMID 37868811, 2023). "Psoriasis is mainly driven by Th17 cells and IL-17, whereas atopic dermatitis is linked to Th2-associated inflammation, IL-4 and IL-13." (PMID 36937045, 2023). "For instance, the expression of filaggrin is downregulated by the interleukins IL-4 and IL-13, which are pathogenic for atopic dermatitis, as well as by IL-17A, which is pathogenic for psoriasis." (PMID 36362566, 2022). "Humanized antibodies against IL-13, IL-4, and IL-31 proved effective in treatment of itch-associated atopic dermatitis but remain to be validated in chronic itch." (PMID 36077340, 2022). "In various adult studies, vitD has been shown to inhibit and stimulate IL-4 activation in various immune responses and has been investigated as a treatment for IL-13-associated atopic dermatitis." (PMID 35334923, 2022). "The onset of atopic dermatitis is due to an antigen disturbing the balance of Th1/Th2 cytokines to cause overproduction of Th2 cytokines such as IL-4, IL-5, and IL-13, while stimulating the B cells to increase the serum IgE level." (PMID 35694270, 2022).
atopic dermatitis (continued). "Atopic dermatitis has a strong Th2 component associated with IL-4 and IL-13 over-production by Th2-polarized lymphocytes in the acute phase of the disease." (PMID 33806193, 2021). "Psoriasis is a disease driven by Th17 cells associated with IL-17 activation, while atopic dermatitis has a strong Th2 component associated with IL-4 and IL-13 overproduction." (PMID 32873845, 2020). "The underlying pathology of atopic dermatitis revolves mainly around type 2 immune-mediated reaction, with cytokines interleukin-4 (IL-4) and interleukin-13 (IL-13) playing a key role in its pathogenesis." (PMID 32382467, 2020). "Although the presence of maternal atopic dermatitis (AD) was associated with increased gestational IL-13 concentrations [adj." (PMID 31428082, 2019). "Atopic dermatitis has also been linked to variants within the genes encoding the T2 pathway-associated cytokines/cytokine receptors IL-4, IL-13, IL-4RA, and IL-31 and associated downstream molecules like STAT6 and GATA3." (PMID 31028434, 2019). "Reduced inflammation was confirmed histologically and by reduced concentrations of cytokines, which are frequently associated with atopic dermatitis (IL-4, IL-13, TARC) and cytokines for which a major role in the mediation of itch has been described (TSLP)." (PMID 29970189, 2018). "Application of dTBP2 inhibited the mRNAs levels of proinflammatory cytokines such as IL-6 well as Th2-related cytokines/chemokines associated with pathogenesis of atopic dermatitis including IL-4, IL-5, IL-13, TSLP, MCD, and TARC." (PMID 28134765, 2017). "Compared with extrinsic atopic dermatitis, the intrinsic form is associated with less IL-4 and IL-13 production." (PMID 28216598, 2017). "Several markers are employed to measure the severity of clinical symptoms of experimental atopic dermatitis including degree of scratching, pruritic skin lesion, and levels of pathogenic cytokines including IL-4, IL-5, IL-13 and IFN-γ." (PMID 24499290, 2013). "Atopic dermatitis has been associated with the Th2 phenotype and dominance of IL-4, IL-5, and IL-13 secretion." (PMID 21303540, 2011). "Additionally, reports have linked nemolizumab to exacerbations of atopic dermatitis (AD), BP, and urticaria - conditions primarily driven by Th2 cytokines such as IL-4, IL-5, and IL-13." (PMID 40104458, 2025). "Furthermore IL‐13, associated with atopic dermatitis pathogenesis was also upregulated in an ageing fibroblast population, which has been linked to barrier function impairment." (PMID 39377615, 2025). "Atopic dermatitis is caused by chronic inflammation of the skin tissue, and the onset of atopic dermatitis is closely related to various inflammatory mediators such as IL-4, IL-13, CCL5, CCL17, and CCL22." (PMID 39599592, 2024). "Recent findings suggest that IL-4 and IL-13 play an important role in the downregulation of inflammatory processes underlying atopic dermatitis pathology and may favorably regulate the disease course." (PMID 38921035, 2024). "Dupilumab is currently used in atopic dermatitis both for its IL-4 and IL-13 effects and could be tested in association with antiparasitic drugs." (PMID 37575260, 2023). "IL-13 is associated with severe iRAEs, and Tralokinumab, approved for atopic dermatitis, may be the treatment of choice for severe iRAEs." (PMID 37081866, 2023). "The interleukins IL-4 and IL-13 reduce the expression of filaggrin and weaken the permeability barrier of keratinocytes; these effects might be responsible for the pathogenic actions of IL-4 and IL-13 in atopic dermatitis." (PMID 36362566, 2022). "Chronic ILC2 activation was reported to contribute to a large variety of tissue inflammatory disorders such as asthma in the lung and atopic dermatitis in the skin, which are generally associated with over-production of the type 2 inflammatory cytokines such as IL-4, IL-5, and IL-13." (PMID 28271445, 2017). "IL-13 has been shown to be involved in HBD-3 deficiency in atopic dermatitis." (PMID 24498256, 2014).
atopic dermatitis (continued). "It has been suggested that the increased expression of IL-4 and IL-13 in atopic dermatitis skin may explain the susceptibility to bacterial and viral skin infections by reducing antimicrobial peptide expression." (PMID 23193414, 2012). "This could be attributed to higher IL-13 levels in patients with severe COVID19.IL-13 is a critical TH2 cytokine linked to atopic dermatitis exacerbations, which could explain the link between severe COVID-19 infection and worsening of atopic dermatitis control/severity." (PMID 41231867, 2025). "Notably, dupilumab’s mechanism of action overlaps with the inflammatory pathways involved in atopic comorbidities, such as atopic dermatitis, allergic rhinitis, and chronic rhinosinusitis with nasal polyps, all of which are associated with elevated levels of IL-4 and IL-13 cytokines." (PMID 40843371, 2025). "The association that GD has with atopic dermatitis has raised suspicion of a potential immune-mediated pathogenesis, and has consequently encouraged some clinicians to treat refractory GD with immune-modulators like dupilumab, an interleukin (IL)-4 and IL-13 inhibitor." (PMID 40861695, 2025). "Background/Objective: Tralokinumab, a monoclonal antibody targeting interleukin-13, is an effective treatment for atopic dermatitis (AD)." (PMID 41682798, 2026). "Central mediators of this axis include IL-4, IL-13, and IL-31, which play crucial roles in driving inflammation in atopic dermatitis." (PMID 41002407, 2025). "Molecular targeted therapies, including advanced atopic dermatitis (AD) treatment with Janus kinase 1 inhibitors (JAK1i) and anti-interleukin-13 antibodies (IL-13Ab), are emerging as effective options." (PMID 40861471, 2025). "The late-stage atopic dermatitis–asthmatic pattern is defined as immune dysregulation driven by Th2 cells, characterized by elevated levels of interleukin (IL)-4, IL-13, and IL-5." (PMID 41155390, 2025). "Dupilumab, a monoclonal antibody that targets interleukin-4 and interleukin-13, is one of the approved biologic treatments for moderate-to-severe atopic dermatitis." (PMID 39906475, 2025). "Chronic Th2-skewed inflammation in atopic dermatitis, characterized by sustained IL-4, IL-13, and IL-6 signaling, can disrupt the BBB, promote microglial activation, and induce neuroinflammatory cascades that impair Aβ clearance." (PMID 41465136, 2025). "Therapies targeting the cytokines IL-4 and IL-13, key mediators of the Th2-dependent immune pathway, play a crucial role in the treatment of atopic dermatitis." (PMID 41002407, 2025). "IL-13 inhibitors (biologics): Treating with IL-13 blockers is effective in managing atopic dermatitis that is moderate to severe." (PMID 40734872, 2025). "- Atopic dermatitis is primarily Th2-driven, characterized by IL-4, IL-13, TSLP, and IL-33, promoting eosinophil and mast cell infiltration." (PMID 41479908, 2025). "In atopic dermatitis, chronic elevation of cytokines such as IL-4, IL-13, and IL-6 perpetuates a Th2-skewed immune response that extends beyond the skin, leading to persistent systemic inflammation." (PMID 41465136, 2025). "Tralokinumab is a fully human monoclonal antibody that targets interleukin-13 (IL-13), a key cytokine involved in the Th2 immune response that drives inflammation in atopic dermatitis." (PMID 41002407, 2025). "Interleukins IL-4, Il-5, IL-10, IL-13 and IL-33 play an important role in atopic dermatitis patients." (PMID 40771803, 2025). "Tralokinumab and lebrikizumab, antibodies blocking IL-13, were approved for the treatment of severe atopic dermatitis." (PMID 41294800, 2025). "IL-4 and IL-13 are type 2 cytokines involved not only in the inflammatory pathways of atopic dermatitis but also in regulating the tumor microenvironment." (PMID 40981274, 2025). "Atopic dermatitis is characterized by disrupted skin barrier function and elevated levels of pro‐inflammatory cytokines, such as IL‐4, IL‐5, and IL‐13." (PMID 40536117, 2025).